ENSG00000267335 (novel protein)
Gene: Protein-coding gene on chromosome 19 (49,022,953 to 49,036,895, reverse strand). Ensembl gene ENSG00000267335.
Genetic constraint (gnomAD): Loss-of-function variants: 0 observed, 0.44 expected, observed/expected ratio (o/e) 0, 90% interval 0 to 1.85. That is too few expected variants to judge how well the gene tolerates losing a copy. Missense variants: 14 observed, 39.98 expected, observed/expected ratio (o/e) 0.35, 90% interval 0.23 to 0.55. Synonymous variants: 4 observed, 13.09 expected, observed/expected ratio (o/e) 0.31, 90% interval 0.15 to 0.7.